CEACAM6 (CEA cell adhesion molecule 6)
Diseases named in the same sentence as CEACAM6 in open-access papers (continued):
Sharing a sentence is not in itself a finding about the gene and the disease.
intrahepatic cholangiocarcinoma (1 paper, 2006). A carcinoma that arises from the intrahepatic bile duct epithelium in any site of the intrahepatic biliary tree. "CEACAM6 expression status was determined and analysed with respect to various clinicopathological parameters in 23 intrahepatic cholangiocarcinomas." (PMID 16868542, 2006). "The purpose of this study was to investigate the clinicopathological and biological significance of human carcinoembryonic antigen-related cell adhesion molecule 6 (CEACAM6) gene expression in human intrahepatic cholangiocarcinoma." (PMID 16868542, 2006). "The clinical implications of CEACAM6 in patients with intrahepatic cholangiocarcinoma were evaluated by comparisons between these two groups." (PMID 16868542, 2006). "The expression of CEACAM6 mRNA in cancer and noncancerous tissues of the patients with intrahepatic cholangiocarcinoma was examined by RT–PCR and real-time PCR." (PMID 16868542, 2006).
lung disease (1 paper, 2015). "In order to evaluate the generality of the CEACAM6 response to various types of lung injury, we used other injury models relevant to infant lung disease." (PMID 26702074, 2015). "Production appeared to be up‐regulated during neonatal lung disease, perhaps related to roles of CEACAM6 in surfactant function, cell proliferation and innate immune defense." (PMID 26702074, 2015).
lymph node tumor (1 paper, 2024). "Interestingly, CEACAM5 and CEACAM6 were absent in metastatic lymph node tumor tissue, compared to a matched primary tumor sample." (PMID 38502695, 2024).
meningioma (1 paper, 2023). A generally slow growing tumor attached to the dura mater. "In addition, KLF4 meningiomas had high expression of carcinoembryonic antigen family members CEACAM6 and CEACAM5." (PMID 36937440, 2023). "AKT1 meningiomas displayed high relative levels of HTRA1 and transferrin genes relative to KLF4 tumors, while KLF4 tumors overexpressed CEACAM6, DEGS2, and TSPAN12 relative to AKT1 tumors." (PMID 36937440, 2023).
nutritional deficiency (1 paper, 2017). "However, advanced-stage GC is characterized by a marked reduction in the number of immune cells, serious nutritional deficiency, and microenvironmental disorder, with a concomitant increase in CEACAM6 expression." (PMID 28883649, 2017).
Obesity (1 paper, 2023). Accumulation of substantial excess body fat. "Many of the upregulated immature neutrophil genes (e.g., OLFM4, DEFA1, ELANE, CEACAM6, CEACAM8, CTSG) have been found to be differentially expressed in persons with obesity and type 2 diabetes, both common comorbidities with psychotic disorders." (PMID 37147304, 2023).
oral cancer (1 paper, 2025). "Similarly, CEACAM6 interacts with EGFR to modulate signaling in oral cancer upon ligand activation." (PMID 40856433, 2025).
Plasma Cell Disorders (1 paper, 2019). "Thus, the quantification of CEACAM6 levels in the blood might be a valuable diagnostic tool to speed up the diagnosis of a malignant plasma cell disorder in individuals with widespread, uncharacteristic clinical symptoms and thus potentially decreasing morbidity and even mortality." (PMID 30809317, 2019).
primary immunodeficiency (1 paper, 2025). "In contrast, low CEACAM6 expression was enriched in immune-related pathways such as chemokine signaling pathway, cytokine-cytokine receptor interaction, hematopoietic cell lineage, leishmania infection, and primary immunodeficiency." (PMID 40936892, 2025).
prostate adenocarcinoma (1 paper, 2015). "Adenocarcinomas from the urinary bladder and urethra were CEACAM6 positive, whereas all prostate adenocarcinomas were CEACAM6 negative." (PMID 25427744, 2015).
prostate carcinoma (1 paper, 2007). A carcinoma that arises from epithelial cells of the prostate gland. "However, CEACAM6 expression was similar in prostate cancer and normal tissues." (PMID 17201906, 2007). "Furthermore, CEACAM6 may be a useful antigen to target in select subtypes of solid tumors, with the exception of prostate cancer, where no differentiation was seen, compared to normal prostate." (PMID 17201906, 2007). "Similar expression of CEACAM6 was found in stage-II, -III, and -IV prostate cancer (3.3–3.8), and was not significantly different from non-neoplastic prostate tissue (P = NS)." (PMID 17201906, 2007).
prostate tumor (1 paper, 2007). "Eighteen stage-II, 15 stage-III, and 4 stage-IV prostate tumor cores were stained for CEACAM5 and CEACAM6." (PMID 17201906, 2007).
rheumatoid arthritis (1 paper, 2022). A chronic, systemic autoimmune disorder characterized by inflammation in the synovial membranes and articular surfaces. "The proportion of peripheral blood CEACAM-positive monochytes, especially CEACAM6-positive monocytes were significantly higher in SSc than that in rheumatoid arthritis (RA) or in HCs." (PMID 36341379, 2022). "CEACAM6-positive cells among classical monocytes were significantly increased in patients with SSc compared with HCs and patients with rheumatoid arthritis." (PMID 36341379, 2022).
scleroderma (1 paper, 2022). Scleroderma is a rare autoimmune connective tissue disorder characterized by abnormal hardening of the skin and, sometimes, other organs. "Some infiltrated CD14-positive monocytes were colocalized with CEACAM6, indicating that CEACAM6-positive monocytes infiltrated the scleroderma dermis." (PMID 36341379, 2022). "Therefore, we analyzed scleroderma skin and observed infiltration of CEACAM6-positive monocytes into the dermis." (PMID 36341379, 2022).
tuberculosis (1 paper, 2022). A chronic, recurrent infection caused by the bacterium Mycobacterium tuberculosis. "CEACAM6 transcript levels were not increased in patients with tuberculosis." (PMID 39239252, 2022).
tubular adenocarcinoma (1 paper, 2024). An infiltrating adenocarcinoma in which the malignant cells form tubular structures. "In addition, high levels of CEACAM6 are suggested as a screening parameter especially for eCCA, which is consistent with our data showing overexpression of CEACAM6 in LD-iCCA, as LD-iCCA are generally mucin-secreting tubular adenocarcinomas resembling perihilar and distal CCA." (PMID 39034327, 2024).
tumor (143 papers, 2004 to 2026). "Tumor acidity is emerging as a hallmark of cancer and carcinoembryonic antigen-related cell adhesion molecule 6 (CEACAM6) expression is frequently increased in acidic tumors." (PMID 40860822, 2025). "Both CEACAM5 and CEACAM6 are tumor-associated antigens that play important roles in cell adhesion and tumor cytochemical sensitivity." (PMID 38796667, 2024). "Another interesting aspect related to the targeting of CEACAM5/6 by CAR T-cells is the potential effects of this therapy on tumor-associated neutrophils, as these cells express high levels of CEACAM6." (PMID 38279989, 2024). "Intriguingly, CEACAM6 overexpression caused less adhesion of tumor cells to the endothelium of pulmonary blood vessels starting the first day after tumor cell injection." (PMID 39468006, 2024). "A recent study also demonstrated that tumor‐associated CEACAM6 cfRNA was present in CSF samples from NSCLC‐LM patients." (PMID 36082960, 2023). "CEACAM6 inhibits this process, and thus higher expression has been correlated to loss of tumour cell differentiation—a process typical and characteristic of tumorigenesis and metastasis." (PMID 34830751, 2021). "In 2016, a study showed that the fluorescent-labeled anti-CEACAM6 probe (CEACAM6-Alexa Fluor488) can label the tumors in patient-derived tumor xenografts (PDTX), however, its diagnostic value in preneoplastic lesion has not yet been investigated." (PMID 34221964, 2021). "Dysregulated overexpression of CEACAM6 is oncogenic and associated with an invasive tumor phenotype." (PMID 32536039, 2020). "Although KRAS mutations are a major driver of PDA, CEACAM6 KO in KRAS mutant PDA cells severely compromised tumor growth." (PMID 31797958, 2019). "It has been suggested that CEACAM6 is associated with tumor progression stage, inhibition of cell differentiation and anoikis, and promotion of cell adhesion, invasion, and metastasis." (PMID 30240439, 2018). "Another report demonstrated an increase in tumor susceptibility in CEACAM6-transgenic mice after AOM treatment, suggesting a role of fimbriae (without specifying the bacterial strains) in colon tumorigenesis." (PMID 30413188, 2018). "In univariate analyses, CEACAM1, CEACAM5 and CEACAM6 expression showed significant association with primary tumor site, while EPHA2 expression was associated with both lymphatic and venous invasion." (PMID 29262644, 2017). "CEACAM6-siRNA or yCDglyTK alone has the potential to kill cancer cells and cause tumor growth delay, as well as inhibit tumor invasion and migration." (PMID 23251258, 2013). "CEACAM5 and CEACAM6 are two tumor-associated antigens that play important regulatory roles in cell adhesion and in tumor cell chemosensitivity." (PMID 17201906, 2007). "The tumours with elevated CEACAM6 expression showed a tendency to be associated with lymphatic invasion and stage of the disease." (PMID 16868542, 2006). "However, CEACAM6 expression in healthy tissues tends to be 1–2 log lower than expression in malignant cells, which decreases the overall risk for off-tumor toxicities." (PMID 38279989, 2024). "However, the association of CEACAM6 with tumour hypoxia is yet to be explained, and the present study is the first to document the association of CEACAM6 with cancer hypoxia." (PMID 39660488, 2024). "CEACAM6 expression associated with cancer cell proliferation, migration, invasion, and angiogenesis, plays an important role in several cancers’ progression, tumorigenesis, tumor cell adhesion, invasion, and metastasis." (PMID 36079985, 2022). "Of note, CEACAM6 expressed by tumor Tregs, has been associated with cancer progression." (PMID 32601304, 2020). "The Ehi cells highly express oncogenic cell–cell adhesion molecules, such as carcinoembryonic antigen-related cell adhesion molecule 5 (CEACAM5) and CEACAM6 that associate with E-cadherin, resulting in increased tumor cell cluster formation and metastatic seeding." (PMID 31331982, 2019).
tumor (continued). "This indicates that CEACAM6, which is associated with tumor progression stage, may regulate cancer progression through different mechanisms in these two tumor subtypes." (PMID 30240439, 2018). "Inoculation of NC101 strain (a mouse isolate of pks-positive E.coli) increased colon inflammation and intestinal crypt proliferation in human CEACAM6-transgenic mice, and caused DNA damage in colonocytes and promoted tumor growth in AOM-treated IL-10(-/-) mouse models." (PMID 30413188, 2018). "Proof of principle for this hypothesis is shown by the reduction in phospho-S437 AKT induced by knockdown of CEACAM6 and the loss of CEACAM6+ve foci in tumours treated with cytotoxic doses of PI3K inhibitors." (PMID 23021083, 2012). "Moreover, CEACAM6 positivity was often associated with keratin pearls within the tumour samples." (PMID 23021083, 2012). "Here, for example, we can see that CEACAM6 has high expression in the smaller noninvasive tumor region at the bottom, while CDH2 (N-cadherin) and DCAF7 have high expression in the larger invasive tumor region at the top." (PMID 41160880, 2026). "All the in vivo results indicated that 131I‐tinurilimab was gradually accumulated in CEAMCA6‐positive xenografts and efficiently eliminated CEACAM6‐positive tumor cells." (PMID 40178153, 2025). "Multiple studies have reported that CEACAM6 is frequently overexpressed in PDAC and is associated with tumor progression, metastasis, and poor clinical outcomes." (PMID 40282889, 2025). "CEACAM6 is frequently overexpressed in some types of cancer, such as pancreatic, lung and colorectal cancers, and is considered as a promising tumour marker." (PMID 40232301, 2025). "CEACAM6 overexpression has been detected in various types of cancers and is correlated with a poorer prognosis, making it the most specific tumor marker within the CEACAM family." (PMID 41233805, 2025). "Conversely, the enrichment of immune-related pathways in CEACAM6-low tumors, particularly those involving chemokine signaling and antigen presentation, suggests a more immune-permissive tumor microenvironment." (PMID 40936892, 2025). "Specifically, we demonstrated that microRNA-29a (miR-29a) functions as a tumor suppressor in NSCLC by regulating CEACAM6, suggesting that the miR-29a–CEACAM6 axis is a potential therapeutic target." (PMID 40282889, 2025). "L-DOS47 is thus both targeted to CEACAM6-expressing tumors and designed to improve tumor control by neutralizing the acidic tumor microenvironment (TME) through ammonia and bicarbonate production from local urea." (PMID 40860822, 2025). "The xenograft tumor models of CEACAM6‐positive (A549) and CEACAM6‐negative (Huh7) were established to further assess the specificity of 89Zr‐Df‐tinurilimab in targeting CEACAM6‐positive tumors in vivo." (PMID 40178153, 2025). "In T_EP, there was significant upregulation of genes associated with malignancy, such as EPCAM, HSPB1, CEACAM6, MUC1, and LY6E, implicating their roles in tumor initiation." (PMID 40786043, 2025). "Western blotting and immunofluorescence analysis revealed that CEACAM6 was significantly overexpressed in A549 cells compared with other tumor cells (such as Huh7, PC9, and H1975), and the Huh7 cell line showed an extremely limited expression of this protein." (PMID 40178153, 2025). "This is the first study to introduce a novel therapeutic approach utilizing a pHLIP-mediated RNA delivery system to enhance the specificity and efficacy of CEACAM6-targeted therapy within an acidic tumor microenvironment in a PDAC model." (PMID 40282889, 2025). "All the results revealed that 131I‐tinurilimab was potentially capable of inhibiting the proliferation and deterioration of CEACAM6‐positive xenograft tumor cells through promoting DNA damage and inducing apoptosis." (PMID 40178153, 2025). "Preclinical studies have demonstrated the therapeutic potential of CEACAM6, showing that its downregulation suppresses tumor growth and increases cancer-cell sensitivity to chemotherapy." (PMID 40282889, 2025).
tumor (continued). "Anti-CEACAM6 mAb 8F5 has a significant synergistic effect when used in combination with the chemotherapy drug paclitaxel, showing 80% tumor growth inhibition in vitro xenograft models." (PMID 38796667, 2024). "High expression of LCN2 in neutrophil‐2 positively regulated the expression of VEGF to stimulate angiogenesis, and CEACAM6 induced neutrophil‐2 to adhere to the endothelial cells, further involving in angiogenesis and tumour progression." (PMID 39021279, 2024). "CEACAM6 levels were very low in stage I tumor samples, but increased markedly with later tumor stages." (PMID 38502695, 2024). "In this study, we show in a murine orthotopic PDAC model that L-DOS47, an immunoconjugate that binds specifically to CEACAM6-expressing tumor cells, counters acidosis by raising pHe locally through the ureolytic activity of its urease enzyme moiety." (PMID 38398062, 2024). "CEACAM6’s surface localization and low expression in normal tissues makes it a promising antigen for therapies targeting acidic tumor regions, particularly if these are also hypoxic." (PMID 38502695, 2024). "The number of Ki67-positive cells per lung area was reduced in the CEACAM6 expressing group due to a lower number of tumor cells." (PMID 39468006, 2024). "In summary, all the results confirm that targeting CEACAM6 expression have tumor inhibitory effects, and the combination of targeted inhibitors and chemotherapy drugs is feasible." (PMID 38796667, 2024). "Detection of carcinoembryonic antigen-related cell adhesion molecule 6 (CEACAM6) and integrin α5β1 was used for tumor colonization." (PMID 39351063, 2024). "While it is already known that CEACAM5 is highly expressed in multiple tumor types, with lower expression levels in primary epithelial cells, the role of CEACAM6 is less established, although prognostic value has been demonstrated." (PMID 38502695, 2024). "The spatial locations of tumor cells align with the H&E image and the expression of CEACAM6, a tumor marker gene." (PMID 39764138, 2024). "Increased signaling related to regulation of actin cytoskeleton, cell and focal adhesion, tumor microenvironment signaling, wound healing, and suppressed inhibition of MMPs in CEACAM6 expressing GB-d1 cells were also observed." (PMID 39468006, 2024). "Targeting CEACAM6, either by inhibiting its function or using it as a means for directing other therapeutic payloads to the tumor microenvironment, is a promising research avenue." (PMID 38502695, 2024). "Taken together, these findings suggest that CEACAM6 plays a crucial role in tumor progression by promoting EMT development." (PMID 38796667, 2024). "In this comprehensive review, we delve into the multifaceted role of CEACAM6 within the tumor microenvironment, highlighting its functional significance in tumorigenesis." (PMID 38796667, 2024). "This is also the first demonstration that a monoclonal antibody against CEACAM6 can inhibit tumor growth in a tumor model." (PMID 38796667, 2024). "SdAb, a single-domain antibody against CEACAM6 2A3, was designed to delay the proliferation, invasive and formation of tumor blood vessels of BXPC3 cells." (PMID 38796667, 2024). "This provocative work suggests a potential role for overexpression of CEACAM6 on the surface of NSCLC cells in permitting CSF invasion in a tumor type–specific manner." (PMID 38451255, 2024). "Lysine lactylation partially explains the upregulation of carcinoembryonic antigen‐related cell adhesion molecule‐6 (CEACAM6) in a lactate‐rich tumour microenvironment." (PMID 39456119, 2024). "We demonstrated previously that miR-29a acts as a tumor suppressor in NSCLC by targeting carcinoembryonic antigen-related cell adhesion molecule 6 (CEACAM6)." (PMID 37684602, 2023). "Intriguingly, we made an interesting finding that the accumulation of CEACAM5+/CEACAM6+ ductal cells was associated with poor overall survival in PDAC patients, highlighting the tumor-promoting function of these two ductal cell clusters." (PMID 37612267, 2023).